CDKN1B (cyclin dependent kinase inhibitor 1B)
Diseases named in the same sentence as CDKN1B in open-access papers (continued):
Sharing a sentence is not in itself a finding about the gene and the disease.
seminoma (2 papers, 2020 to 2025). A radiosensitive malignant germ cell tumor found in the testis (especially undescended), and extragonadal sites (anterior mediastinum and pineal gland). "In summary, analysis of AACR Project GENIE data sheds light on a distinct seminoma genomic profile characterized by recurrent mutations in KIT, KRAS, and MTOR, as well as focal copy number alterations in CDKN1B, KRAS, CCND2, and H3F3C." (PMID 41154418, 2025). "Among them, we found the cell cycle- and CDK4/6-associated genes CCND2 (seminomas 9.8%, non-seminomas 16.8%), CDKN1B (P27; seminomas 15.3%, non-seminomas 16.4%) and MDM2 (seminomas 4%, non-seminomas 3.6%) commonly amplified in seminomas and non-seminomas." (PMID 32418994, 2020).
serous ovarian carcinomas (2 papers, 2008 to 2012). "In addition, miR-31 inhibits the proliferation of serous ovarian carcinomas and other cancers, and the PLZF-microRNA-221/-222 pathway controls the progression of melanoma neoplasia through the down-modulation of p27Kip1/CDKN1B and the c-KIT receptor." (PMID 22942733, 2012).
skin cancer (2 papers, 2018 to 2022). "For example, the RB1 pathway is a primary driver of skin cancers, with mutations in RB1, CDKN2A/p16, CDKN1A/p21, CDKN1B/p27, CDKN2B/p15, CCNE1/cyclin E, and CCND1/cyclin D, collectively, in 26.4% of melanomas." (PMID 34983823, 2022).
tongue squamous cell carcinoma (2 papers, 2017 to 2021). A squamous cell carcinoma that arises from the tongue. "Similarly, the miR-24-mediated downregulation in DND1 expression level inhibited the expression of cyclin-dependent kinase inhibitor 1B (CDKN1B) and resulted in enhanced proliferation and reduced apoptosis in tongue squamous cell carcinoma (TSCC) cells." (PMID 34721738, 2021). "Moreover, Dnd1 expression change mediated by miR-24 could suppress the expression of cyclin-dependent kinase inhibitor 1B (CDKN1B) and also led to enhanced proliferation and reduced apoptosis in tongue squamous cell carcinoma cells." (PMID 28191469, 2017).
uveal melanoma (2 papers, 2023 to 2024). A melanoma derived from melanocytes of the uveal tract. "Indeed, in a TCGA pan-cancer analysis, uveal melanoma had one of the strongest associations between patient outcomes and CDKN1B mRNA expression, with higher expression observed in patients with higher rates of metastasis." (PMID 39123378, 2024). "However, a high DFS prognosis for uveal melanoma (UVM) was associated with a low-expression group of the CDKN1B gene." (PMID 37432583, 2023).
ZIKV infection (2 papers, 2018 to 2022). "SaliPhe, obatoclax, and gemcitabine were evaluated by their activity on two signaling phosphoproteins which are mainly affected by ZIKV infection, i.e., the transcription factor cAMP response element binding protein (CREB) and the cyclin-dependent kinase inhibitor 1B (p27)." (PMID 29758005, 2018).
carcinoid tumours (1 paper, 2020). "Radiological examinations such as MRI or CT are helpful to detect pituitary, pancreatic, adrenal or carcinoid tumours while DNA analysis helps ascertain germline mutations including MEN1, RET and CDKN1B." (PMID 31797261, 2020).
cataract (1 paper, 2017). Partial or complete opacity of the crystalline lens of one or both eyes that decreases visual acuity and eventually results in blindness.
cervix adenocarcinoma (1 paper, 2015). "We carried out subcellular localization experiments by transfection with plasmid vectors expressing the WT or mutant CDKN1B cDNA into the eukaryotic human cervix adenocarcinoma (HeLa) and GH3 cell lines." (PMID 25416039, 2015).
colorectal adenoma (1 paper, 2019). An adenoma that arises from the colon or rectum. "There is limited data on the expression of target genes of the miR-200 family in colorectal adenoma and, to the best of our knowledge, only CDKN1B and SOX2 have so far been investigated, excluding studies on dysplastic lesions in inflammatory bowel diseases." (PMID 31623346, 2019).
dilated cardiomyopathy (1 paper, 2008). Cardiomyopathy which is characterized by dilation and contractile dysfunction of the left and right ventricles. "Comparing EMBs from each 10 patients with dilated cardiomyopathy (DCM) and inflammatory cardiomyopathy (DCMi), T-PreAmp real-time RT-PCR analyses revealed differential regulation regarding 27 (30%) of the investigated 90 genes related to both HPRT-CCM and CDKN1B." (PMID 18194512, 2008).
eosinophilic disorders (1 paper, 2025).
female sterility (1 paper, 2020). "A lack of Cdkn1b (p27KIP1) results in female sterility due to impairment of ovarian follicle development and corpora lutea formation, believed to be related to the oversized pituitary and thus alteration of the hypothalamic–pituitary–ovarian axis which is seen in these KO mice." (PMID 32731332, 2020).
gastric NETs (1 paper, 2024). "Similar to pNETs, menin suppresses the development of gastric NETs through the activation of CDKN1B gene expression." (PMID 39336822, 2024).
goblet cell adenocarcinoma (1 paper, 2023). "Mutations in the CDKN1B gene occur only in some types of cancers, including breast, prostate, and small intestine neuroendocrine tumors and appendiceal goblet cell adenocarcinoma." (PMID 37509254, 2023).
HCMV infection (1 paper, 2024). "Another possibility for hearing damage from HCMV infection is reduced levels of CDKN1B, an enzyme inhibitor that regulates the G1 phase of the cell cycle." (PMID 39205316, 2024). "HCMV infection of human embryonic lung cells leads to CDKN1B degradation." (PMID 39205316, 2024).
histiocytic neoplasm (1 paper, 2018). Histiocytic tumors are a heterogeneous group of tumors and tumorlike masses commonly associated with histologically identical extracranial lesions.
Hodgkins lymphoma (1 paper, 2021). A heterogeneous group of malignant lymphoid neoplasms of B-cell origin characterized histologically by the presence of Hodgkin and Reed-Sternberg (HRS) cells in the vast majority of cases. "Thus, it was shown that Hodgkin’s lymphoma cells can have a high level of miR-24-3p, which limits the expression of CDKN1B/P27kip1 and MYC genes and also protects cells from apoptosis." (PMID 34440124, 2021).
Infertility (1 paper, 2019). "Indeed, we found that 1 out of 6 Cdkn1b-/- (F1xF1) females tested was fertile, in contrast to the complete infertility observed in female Cdkn1b-/- mice." (PMID 30893315, 2019). "A potential explanation for these seemingly contradictory findings could be due to the abnormal ovarian function and infertility of female Cdkn1b-/- mice necessitating mammary fat pad transplantation assays to assess mammary gland development." (PMID 30893315, 2019).
leiomyosarcoma (1 paper, 2025). An uncommon, aggressive malignant smooth muscle neoplasm, usually occurring in post-menopausal women. "We sought to investigate the potential of miR-221, miR-320a, miR-133a, and miR-133b, along with their target mRNAs CDKN1B, TGFBR1, and IGF1R, as candidate biomarkers of leiomyosarcoma." (PMID 40630212, 2025). "The expression levels of miR-221, miR-320a, miR-133a, and miR-133b as well as their target mRNAs CDKN1B, TGFBR1, and IGF1R were assessed by quantitative real-time reverse transcription polymerase chain reaction (qRT-PCR) in tissue samples from 33 patients with leiomyosarcoma." (PMID 40630212, 2025). "The target mRNAs CDKN1B, TGFBR1, and IGF1R in 25 leiomyosarcoma tumor tissues were not significantly deregulated." (PMID 40630212, 2025).
lung carcinoid (1 paper, 2017). "One patient with lung carcinoid with Ki-67 < 5% without evidence of an inherited syndrome had somatic mutations detected including PDGFRB A366T and CDKN1b loss, and had best response of stable disease on treatment." (PMID 29262620, 2017).
lung fibrosis (1 paper, 2024). "Also, FPNI treatment prevented the upregulation of senescence markers that are well-known to be associated to lung fibrosis, such as TNF-α, Il6, Cdkn1a and Cdkn1b along with that of collagen isoforms Col1a1 and Col3a1." (PMID 38167804, 2024).
lymphoproliferative syndrome (1 paper, 2023). A disorder characterized by proliferation of lymphocytes at various stages of differentiation. "These genes include HEXA (Tay-Sachs disease), CDKN1B (Neoplasia), GATA1 (Thrombocytopenia, Thalassemia), and SH2D1A (Lymphoproliferative syndrome)." (PMID 38033082, 2023).
membranous nephropathy (1 paper, 2026). "Proteomic-wide MR revealed MTR as protective in chronic GN and HCK as a risk factor for membranous nephropathy, whereas CD302 and CDKN1B showed protective effects." (PMID 41990104, 2026).
metastatic prostate carcinoma (1 paper, 2019). A carcinoma that arises from the prostate gland and has spread to other anatomic sites.
myeloproliferative neoplasm (1 paper, 2015). A clonal hematopoietic stem cell disorder, characterized by proliferation in the bone marrow of one or more of the myeloid (i.e., granulocytic, erythroid, megakaryocytic, and mast cell) lineages. "Here, we show that the combined inactivation of Pten and Cdkn1b results in a more severe myeloproliferative neoplasm phenotype associated with lower hemoglobin, enlarged spleen and liver, and shorter lifespan compared to inactivation of Pten alone." (PMID 27366593, 2015).
neuropathy (1 paper, 2024). A disorder affecting the nervous system that manifests with pain, tingling, numbness, and/or muscle weakness. "Specific genes increased in patients withoutlinezolid-associated neuropathy included ATG4C, BAX, and IGF1, while patients onlinezolid who suffered from neuropathy had an increase in AURKB, CASP3, CASP8, CDK1,CDKN1B, CEBPB, NADSYN1, NRF1, GPX7, and SBSN." (PMID 38939039, 2024).
non-Hodgkin lymphoma (1 paper, 2012). Distinct from Hodgkin lymphoma both morphologically and biologically, non-Hodgkin lymphoma (NHL) is characterized by the absence of Reed-Sternberg cells, can occur at any age, and usually presents as a localized or generalized lymphadenopathy associated with fever and weight loss. "Mutations of CDKN1B (p27Kip1) is rare in non-Hodgkin’s lymphoma and ATL." (PMID 23060864, 2012).
orchitis (1 paper, 2021). Inflammation of one or both testes due to viral or bacterial infections.
parathyroid hyperplasia (1 paper, 2025). A hyperplasia that involves the parathyroid gland. "In adolescents, mutations in MENIN (MEN1), RET (MEN2), CDKN1B (MEN4), and CDC73 (HPT-JT) predominate, usually leading to multiglandular parathyroid hyperplasia in syndromic forms of PHPT." (PMID 40666157, 2025).
periodontitis (1 paper, 2024). An acute or chronic inflammatory process that affects the tissues that surround and support the teeth. "The relevant genes that were involved in the PI3K/AKT pathway activation observed in the T2DM-related periodontitis included those that affect apoptosis (e.g., FOXO1, BCL2, and growth differentiation factor 15 [GDF15]) and cell cycle passage (e.g., CDKN1B and CCND1)." (PMID 38241313, 2024).
renal tumor (1 paper, 2018). "Restoring TMIGD1 expression in renal tumor cells stimulated phosphorylation of p38MAK, induced expression of p21CIP1 (cyclin-dependent kinase inhibitor 1), and p27KIP1 (cyclin-dependent kinase inhibitor 1B) expression, key cell cycle inhibitor proteins involved in regulation of the cell cycle." (PMID 29515762, 2018).
retinal (1 paper, 2020). "Cdkn1b−/− mice (Cdkn1b is the mouse p27-coding gene) show increased body size, hyperplasia of different organs, retinal dysplasia, neocortex alterations, and female sterility." (PMID 32933137, 2020).
rhabdoid tumor (1 paper, 2009). An aggressive malignant embryonal neoplasm usually occurring during childhood. "Cyclin E can overcome SMARCB1 induced proliferation arrest in RT cell lines also implying involvement of CIP KIP inhibitors in rhabdoid tumor, however in other studies CDKN1A and CDKN1B expression were unchanged by SMARCB1 expression." (PMID 19221586, 2009). "We identified minor transcriptional upregulation of CDKN1A or CDKN1B in two different RT cell backgrounds following transfection with SMARCB1 however, expression of these genes persisted in clinical specimens of ATRT with inactivated SMARCB1 arguing against a major role in rhabdoid tumor aetiology." (PMID 19221586, 2009). "CDKN1C expression was also shown to be generally absent in clinical specimens of rhabdoid tumor, however CDKN1A and CDKN1B expression persisted." (PMID 19221586, 2009).
rhabdomyosarcoma (1 paper, 2025). A rare aggressive malignant mesenchymal neoplasm arising from skeletal muscle. "Similar effects have been reported for SAHA, which downregulates cyclin D1 and upregulates CDKN1A and CDKN1B in rhabdomyosarcoma models, indicating that HDACi broadly regulate cell cycle-associated genes." (PMID 40671124, 2025).
somatotrophinomas (1 paper, 2020). "AHR may also have AIP-independent roles in pituitary tumorigenesis as AHR but not AIP expression is reduced in GNAS-mutated somatotrophinomas, and AHR activation increases the transcription of CDKN1B, which is another tumour suppressor gene implicated in pituitary and other endocrine tumours." (PMID 31996203, 2020).
subarachnoid hemorrhage (1 paper, 2021). A serious neurological disorder characterized by intracranial hemorrhage into the subarachnoid space. "CDKN1B regulates oxyhemoglobin-induced neuronal cell apoptosis and inflammatory responses via miR-502-5p following subarachnoid hemorrhage." (PMID 34516316, 2021).
type 1 diabetic (1 paper, 2022). "The present study revealed that fisetin was a natural agonist of CDKN1B that has potential renal protective effects in both type 1 diabetic animal models and HG-induced podocyte injury." (PMID 35126159, 2022).
uterine cancer (1 paper, 2023). Primary or metastatic malignant neoplasm involving the uterine corpus and/or the cervix. "The majority of CDKN1B mutations (> 3%) were found in uterine cancers with “mutation” as the predominant subtype in patients." (PMID 37432583, 2023).
tumor (492 papers, 1999 to 2026). "Another study that analyzed multiple midgut NEN and metastatic tumors from the same individuals found that the CDKN1B mutation often occurred quite late in tumor development." (PMID 38123518, 2024). "In human HCC, the downregulation of CDKN1B showed prognostic significance associated with advanced tumor stages, lower survival rates, and HCC recurrence." (PMID 38476236, 2024). "Reduced levels of p27KIP1 are commonly observed in tumor samples, and CDKN1B mutations, though rare, have been identified in several cancers." (PMID 39333489, 2024). "We reviewed recent data of MEN4 published cases describing CDKN1B pathogenic variants that have analysed tumour tissue to assess the presence of a possible LOH." (PMID 36334246, 2023). "It is well-known that CDKN1B is a tumor-inhibiting factor that encodes p27kip1, a cyclin-dependent kinase inhibitor." (PMID 37432583, 2023). "CDKN1B controls cell cycle progression to the G1 stage, and in vitro studies have shown CDKN1B levels to be associated with increased tumor size and tumor grade." (PMID 37628978, 2023). "Loss of CDKN1B function or decreased expression has been implicated in various cancer types, leading to uncontrolled cell cycle progression and increased tumor growth." (PMID 38248731, 2023). "Here, we utilized several algorithms, such as XCELL, EPIC and MCPCOUNTER, to investigate the underlying relationship between the amount of cancer-associated fibroblast infiltration and CDKN1B expression in various TCGA tumor types." (PMID 37432583, 2023). "Among cell-cycle regulators, BTG3-associated nuclear protein and cyclin-dependent kinase inhibitor 1B are involved in the cell-cycle G1/S transition, playing tumor-suppressor roles." (PMID 35629968, 2022). "CDKN1B has previously been implicated as a potential tumor suppressor gene in SI-NETs, linking cell cycle dysregulation in their tumorigenesis." (PMID 35922826, 2022). "The overall aim of the present study was to determine if copy number alterations of SMAD4 and CDKN1B in SINETs correlate with corresponding protein expression and can be linked to tumor initiation." (PMID 33509126, 2021). "CDKN1B is a known tumor suppressor gene that is mutated in a small percentage of patients with I-NETs." (PMID 34680217, 2021). "Nevertheless, based on advances in genomic analyses, CDKN1B has been found to be associated with tumor progression." (PMID 32590883, 2020). "Both tumor types involve the alteration of the cell cycle, albeit the implicated genes are different: SiNETs more frequently involve CDKN1B mutation or copy loss, whereas this locus is rarely affected in PanNETs with the exception of patients with MEN4." (PMID 30657883, 2019). "MEN1 encodes menin, which is involved in cell division, genome stability, and gene transcription, whereas CDKN1B encodes p27, which prevents cell cycle progression and acts as a tumor suppressor gene." (PMID 30990521, 2019). "One possibility is that loss of only one allele of CDKN1B in its C-terminal portion is sufficient to drive tumor progression, as already well established in mouse carcinogenesis models." (PMID 30976290, 2019). "CDKN1B has been identified as one of the most frequently somatically altered genes, mutated in three and deleted in sixteen tumor samples." (PMID 30065701, 2018). "Mutations in GEPNETs are rare, and the only identified recurrent gene mutation in SINETs is of CDKN1B, which occurs in less than a tenth of all tumours." (PMID 29444910, 2018). "Despite its central role in tumor progression, for a long time it has been proposed that CDKN1B was very rarely somatically mutated in human cancer and that its expression levels were almost exclusively regulated at post-transcriptional level." (PMID 30065701, 2018). "In a subsequent study, CDKN1B mutations were identified in 8% of tumors, suggesting the gene for p27 to be a putative tumor suppressor in these tumors, with an obvious role in regulating the cell cycle." (PMID 29255447, 2017).